CXCR4 (C-X-C motif chemokine receptor 4)
Diseases named in the same sentence as CXCR4 in open-access papers (continued):
Sharing a sentence is not in itself a finding about the gene and the disease.
cancer (continued). "Mechanistically, activation of CXCR4 leads to the transition to the epithelial–mesenchymal transition (EMT), enhancement of cancer stem cell (CSC) properties, and establishment of a pro-survival phenotype." (PMID 41002447, 2025). "The binding of chemokine stromal cell-derived factor 1 (SDF-1 or CXCL12) to the G-protein coupled receptor CXCR4 activates signaling pathways that lead to the expression of genes involved in EMT, contributing to cancer cell migration, invasion, and metastasis." (PMID 40608162, 2025). "In cancer cells, the binding of SDF-1 to CXCR4 activates processes such as angiogenesis, invasion, and migration." (PMID 40422575, 2025). "mAbs targeting chemokine receptors, such as CXCR4 and CCR5, are being investigated for their potential to prevent metastasis and modulate the TME in the context of cancer." (PMID 40969301, 2025). "The staining intensity of CXCR4 and SDF-1 in cancer cells was significantly higher in intestinal-type than in diffuse-type gastric cancer." (PMID 40485723, 2025). "By interacting with its receptor CXCR4, CXCL12 promotes migration, invasion, and angiogenesis in cancer cells, a chemokine abundantly expressed in the TME." (PMID 39070795, 2024). "The chemokine SDF-1 and its receptor CXCR4 play pivotal roles in the TME, significantly influencing cancer progression and metastasis." (PMID 39195225, 2024). "This feature can be leveraged by a theranostic approach, which provides a read-out of the actual CXCR4 expression in vivo, followed by CXCR4-targeted radioligand therapy (RLT) exerting anti-cancer as well as myeloablative efficacy." (PMID 38190998, 2024). "CD184/CXCR4 is an important marker involved in many cellular conditions and types of cells, and it is expressed in stem cells and cancer cells." (PMID 38982099, 2024). "For example, CXCR4+ iCAFs and CD133+ iCAFs were observed in iCAFs, in which CD133+ iCAFs expressed cancer stem cell markers, including CD133, MET, EPCAM, CD24 and CD44." (PMID 38167055, 2024). "Meanwhile, the single-cell analysis revealed that the presence of the (CK+/CXCR4+/JUNB-) and (CK+/PD-L1+/CD45) phenotypes were correlated with poorer PFS and OS, respectively, providing interesting biomarkers for this type of cancer." (PMID 38727318, 2024). "The cancer cells express various molecules that enable them to stick to and move through vessel walls, with the CXCL12/CXCR4 pathway playing a significant role in directing their migration to specific sites." (PMID 38940900, 2024). "CXCR4 and its endogenous ligand C-X-C motif chemokine 12 (CXCL12) play a crucial role in various immune diseases and cancer progression." (PMID 39162901, 2024). "Chemokine receptor CXCR4 has been extensively studied because of its defined role in immune cell trafficking, HIV infection, inflammatory diseases, and cancer progression." (PMID 39204345, 2024). "PIM1 promotes the phosphorylation and surface expression of CXCR4, supporting the CXCL12–CXCR4 axis responsible for cancer cell proliferation and metastasis." (PMID 39200101, 2024). "Through molecular analyses, we confirmed the presence of CXCR4, the primary receptor of SDF-1, which is instrumental in signal transduction processes that drive cancer progression." (PMID 39195225, 2024). "Tannic acid, a gallotannin found in several natural sources, plays a role in various cancer signaling pathways, including the JAK/STAT, RAS/RAF/mTOR, TGF-β1/TGF-β1R axis, VEGF/VEGFR, and CXCL12/CXCR4 axes." (PMID 39830672, 2024). "Specifically, the CXCL12/CXCR4 axis enhances cancer cell invasiveness and migratory capacity by increasing the expression of EMT markers, whereas CXCR4 knockdown significantly reduces the migration and invasion of PCa cells into osteoblasts." (PMID 39092186, 2024). "Here, we aimed to develop a new CXCR4-targeted PET tracer, and to investigate the translational potential for noninvasive imaging of CXCR4 expression in various cancer entities through preclinical and pilot clinical studies." (PMID 39431004, 2024).
cancer (continued). "The interaction between the CXCL12/CXCR4/ACKR3 axis and the STAT3 signaling pathway is crucial in the development and progression of various diseases, including cancer." (PMID 38920657, 2024). "The SDF-1/CXCR4 axis, which is part of the CXC chemokine family, plays a critical role in cancer progression and metastasis across various malignancies, including CRC." (PMID 39195225, 2024). "However, the optimised copper(II) complexes could be radiolabelled with copper-64 (PET imaging radioisotope) or copper-67 (therapeutic/SPECT imaging radioisotope), offering a route to the development of CXCR4-targeted theranostics for cancer imaging and therapy." (PMID 39204345, 2024). "[68Ga]Ga-Pentixafor and [68Ga]Ga-FAPI-4 are gaining prominence for the diagnosis of overexpressed Chemokine Receptor-4 (CXCR4) and Fibroblast Activation Protein (FAP) receptor, respectively, in the microenvironment of numerous cancer types." (PMID 39050235, 2024). "LNCaP also had significantly lower expression of CXCR4 as compared to DU145; CXCR4 can stimulate cancer cell migration through chemotaxis." (PMID 39741355, 2024). "Pep R also reduced a population of CD133+CXCR4+ cells in HCT116 and HT29 cells, considered stem-resistant cancer cells." (PMID 39070795, 2024). "In animal models of cancer pain, the CXCL12 / CXCR4 axis has been found to mediate the effects of astrocytes on cancer-associated pain." (PMID 39641645, 2024). "These marker genes play diverse roles in cancer, such as promoting growth and proliferation (MYC, HIF1A, ATM), inhibiting apoptosis (MCL1, BIRC3, BCL2) and facilitating invasion (CXCR4, CD55)." (PMID 38982317, 2024). "CXCR4 is the receptor for CXCL12, also called stromal cell-derived factor 1 (SDF1), and is the most widely expressed chemokine receptor in human cancer." (PMID 39114657, 2024). "Likewise, CXCL12 produced in lymph nodes may attract cancer cells or leukocytes expressing CXCR4." (PMID 38835055, 2024). "In most cancers, the proinflammatory E06-veins-SELE demonstrated a decreased abundance from early to late stage; by contrast, E02-tip-CXCR4 showed increased enrichment." (PMID 39345334, 2024). "In previous studies, abnormal CXCR4/CXCL12 signaling was involved in a variety of pathophysiological processes, such as cancer and organismal inflammation." (PMID 39026682, 2024). "CXCR4 expression, a G-protein coupled receptor involved in the epithelial-to-mesenchymal transition (EMT) and cancer stem cell survival, was correlated, in GBM tumors, with a state of progression and therapy resistance." (PMID 39055895, 2024). "Cancer cells induce TGF-β-dependent stimulation of CXCR4 in monocytes, while CXCL12 expressed by perivascular fibroblasts recruits these migratory TAMs to the blood vessels and entrains the motile cancer cells." (PMID 39003350, 2024). "Similarly, CXCL12 produced in lymph nodes may attract CXCR4-expressing cancer cells or leukocytes." (PMID 39195299, 2024). "Pharmacologically blocking CXCR4 or genetically depleting CXCL12 in LECs enhances CD8+ T cell retention and promotes anti-cancer immunity." (PMID 39211044, 2024). "CXCR4 and CCR4 are attractive candidates for cancer studies since they have been reported to modulate physiological processes associated with proliferation, survival, tumor growth, invasions, and epidermal growth factor receptors." (PMID 37489388, 2023). "Intriguingly, using sorted differentiated CD133–FLUO–cancer cells, overexpression of NR5A2 induced upregulation of CD133 and CXCR4, enhanced sphere formation, and, most importantly, markedly enhanced in vivo tumorigenicity." (PMID 38012687, 2023). "Several genes such as CXCR4, APQ1, TACSTD2, and S100A9 have been reported to participate in angiogenesis or are highly expressed in endothelial cells in cancer." (PMID 37626402, 2023). "CXCL12 activates CXCR4 and CXCR7 chemokine receptors, and the signal axis is dysregulated in multiple types of cancer." (PMID 36639681, 2023).
cancer (continued). "These AMD3100-SPNPs treatments blocked the CXCR4/SDF1 alpha pathway in human GBM models in vivo and rodent models of cancer." (PMID 38004925, 2023). "CXCR4 is a specific chemokine receptor of CXCL12, which is highly expressed on human progenitor cells and stem cells, including cancer stem cells." (PMID 36308553, 2023). "This review comprehensively summarizes CXCL12-CXCR4/CXCR7 signaling axis in cancer progression and provides theoretical basis for the potential of CXCL12 and its receptors CXCR4/CXCR7 as cancer therapeutic targets." (PMID 37497001, 2023). "Interestingly, the mRNA level of CXCR4 could be increased by cancer stem-like cells." (PMID 37679408, 2023). "C-X-C chemokine receptor type 4 (CXCR4), also known as CD184, is the most commonly expressed chemokine receptor in malignant tumors." (PMID 36308553, 2023). "Treatment with a CXCR4 antagonist and/or a CXCL16 neutralizing antibody, either alone or in combination, strongly suppressed the migration of cancer cells to brain metastatic CAF aggregates." (PMID 37386445, 2023). "The initial function of CXCR4 discovered is in HIV infection and cancer cell metastasis; its role in development is also very important." (PMID 37628919, 2023). "Regarding the upregulated genes, C-X-C chemokine receptor type 4 (CXCR4) is a G protein-coupled receptor (GPCR) that is expressed on the surface of various cell types, including immune cells, cancer cells, and nervous system cells." (PMID 37538932, 2023). "Our study offers structural basis for the design of ligands able to modulate the formation of CCR5 and CXCR4 dimers and in turn their activity, with therapeutic potential against HIV, cancer, and immune-inflammatory diseases." (PMID 37833254, 2023). "The interaction of CXCR4 and its ligand stromal-derived factor 1α (SDF-1α, also known as CXCL12) mainly secreted by stromal cells promotes several aspects of cancer progression including angiogenesis, metastasis, relapse, drug resistance, and survival." (PMID 36762192, 2023). "CXCR4 (CXC motif chemokine receptor type 4) is a strongly conserved chemokine that is essential for stem cell trafficking, lung repair, and cancer metastasis." (PMID 37705610, 2023). "CXC chemokine receptor 4 (CXCR4) and its ligand CXCL12, both of which are overexpressed in many cancers, play a pivotal role in metastasis." (PMID 37749552, 2023). "Activation of CXCR4 in BC cells by its ligand, CXCL12, promotes chemotaxis and migration of cancer cells towards CXCL12-rich environments, which coincidentally represent the main sites for BC metastasis, namely the bones, lymph nodes, lungs, and liver." (PMID 37253733, 2023). "It is known that CD133+/CXCR4+ cells (cell with both CD133 and CXCR4 antigens present, both being cancer stem cell markers) are responsible for metastasis development." (PMID 37685710, 2023). "Once cancer cells metastasize to the bone, different chemokine motif ligands (CXCL12, CXCR4, CXCL5, CXCR2) promote breast cancer cell colonization within the bone." (PMID 36674719, 2023). "Due to its involvement in the migration of hematopoietic stem cells, its role in dysregulating CXCR4 in various human cancers, and HIV-1’s use of CXCR4 to enter T cells, this receptor is becoming an increasingly important therapeutic target." (PMID 36992255, 2023). "Here, we demonstrated that the shuttle of HIF-1α contained in EVs from cancer-free individuals activates the transcription of CXCR4 that in turn increases the frequency of mesenchymal and disseminating CD133+CXCR4+ MICs." (PMID 37838700, 2023). "Considering the pivotal role of the CXCL12/CXCR4 axis in the complex TME, the development of targeted therapies aimed at disrupting this pathway is needed for efficient cancer treatment." (PMID 38004606, 2023). "Regarding its oncological effects in some of the predominant cancer types, it has previously been postulated that HIV-1 interaction with CXCR4 can render CD4+ cells vulnerable to malignant transformation." (PMID 37489388, 2023).
cancer (continued). "A brief summary of the important genomic findings follows:In liver SM of CR cancer, the expression of VEGF, CXCR4, COX2 mRNA, TGF-α, and ISR1 was found to be significantly higher in SM compared to MM, while that of Cyclin E, CCR6 and FAK significantly lower." (PMID 37340186, 2023). "IFN-γ induced interferon-induced protein with tetratricopeptide repeats 5 (IFIT5), C-X-C Motif Chemokine Receptor 4 (CXCR4) and branched-chain amino acid aminotransaminase 1 (BCAT1) all promote cancer cell stemness and metastasis." (PMID 37503572, 2023). "JUN, CXCR4, and WNT5A were the top three interaction DEGs in pathways in cancer; H6PD, FH, and ACO2, which associate with glucose metabolism, were the top three interaction DEGS in metabolic processes." (PMID 37601754, 2023). "Among these genes, the chemokine receptor CXCR4 and its ligand CXCL12 were widely reported to be involved in cancer cell survival, proliferation, and migration." (PMID 37908977, 2023). "KT alleviates the invasion of cancer cells from blood vessels to bone by inhibiting CXCL5/CXCR2 and CXCL12/CXCR4." (PMID 36674719, 2023). "Overexpression of TSTA3 abnormally activated CXCR4/CXCL12 axis, thereby mediating cancer cell adhesion, metastasis and immune escape." (PMID 37986192, 2023). "Previous studies have reported that both, CXCR4 and CXCR7 promote migration and invasion of several cancer cell lines upon activation by CXCL1213,28." (PMID 37558722, 2023). "Chemokine receptors 7 (CXCR7) and 4 (CXCR4) are G protein-coupled receptors (GPCRs) that can be stimulated by a ligand, CXCL12, in various human cancers." (PMID 36077241, 2022). "Correlations were observed between CREB3L1 expression and several immune biomarkers such as CD28, CXCR4 and KDR in several cancers." (PMID 36171879, 2022). "Some targets, including EGFR, PDGFR, FAK, CXCR4, and MMP9, have corresponding inhibitors that have been approved or are under active clinical trials for cancer treatment." (PMID 35919862, 2022). "Several epigenetic modulators, such as VEGF (vascular endothelial growth factor), CXCR4 (CXC chemokine receptor 4), EPHB2 (EPH Receptor B2), miR-103, or any other sort of long non-coding RNAs, are carried by cancer-derived EVs to stimulate angiogenesis." (PMID 35159299, 2022). "In the top 20 upregulated DEGs of lymph node‐derived exhausted CD8+ T cells, CXCL13, CXCR4, CH25H, HSPD1, HSP90AA1, and ATF3 have been confirmed to promote lymph node metastasis in several cancer types." (PMID 35184420, 2022). "CXCR4 as the most common type of GPCR member stands out for its involvement in several pathological conditions, including immune diseases and cancer." (PMID 35571062, 2022). "The additional observation that cancer cells in these tumors appeared to be “coated” with CXCL12, the ligand for CXCR4, suggested that the cancer cells have specifically adapted to the chemokine/chemokine receptor system." (PMID 35046049, 2022). "We also observed high expressions of Ki67 and CXCR4 BC samples in the ERα36high CAF groups, which suggests their role in cancer cell proliferation and migration." (PMID 35454913, 2022). "Immunohistochemical staining of patient cancer samples revealed heterogeneous expression of CCR7, CXCR4 and CXCR6 with low expression in most primary tumors and strong chemokine receptor expression in metastatic lesions to the liver." (PMID 35203305, 2022). "Many signaling pathways are involved in cancer progression, and among these pathways, the CXCL12 axis and its two receptors CXCR4 and CXCR7 are well described for many cancers." (PMID 35406582, 2022). "In gastric cancer, a subpopulation of cancer stem cells defined by DPP-IV and CXCR4 expression exhibited higher migration, invasion, and clonogenic capacity." (PMID 35565202, 2022). "In summary, our work establishes that CXCL12 signaling controls PKM2, a central regulator of metabolism in proliferating cells, and highlights the effects of CXCR4 and ACKR3 on metabolic reprogramming in cancer." (PMID 35681470, 2022).
cancer (continued). "Understanding pro-tumorigenic phenotype of MSCs and mechanisms of adhesion and heterocellular communication favoring their interaction with cancer PCs, will allow to manipulate critical pathways, including CXCL12/CXCR4 axis, thus improving disease outcome." (PMID 35064098, 2022). "Luciferase complementation data showing the CXCL12-dependent dissociation of PKM2 oligomers suggested that CXCR4 and ACKR3 signaling shifted cancer cells toward glycolysis." (PMID 35681470, 2022). "Here, simultaneous agonist-dependent activation of CXCR4 and CB2 resulted in reduced CXCR4-mediated formation of phosphorylated p42/44 MAPK (P-p42/44) and ultimately diminished cancer cell chemotaxis." (PMID 35277658, 2022). "CD24 in combination with CD44 and/or CD133 (PROM1) has been highlighted as cancer stem cell markers (in combination with NANOG, OCT3/4, and SOX2), and a cell‐type‐dependent correlation of CD24 to the chemokine receptor CD184 (CXCR4) has been shown." (PMID 34293822, 2022). "Our findings point to therapeutic limitations of ongoing efforts to selectively target CXCR3, CXCR4, or CXCR7 in cancer patients, and rather favor individualized targeting strategies." (PMID 36539774, 2022). "CXCR4 is a key player in cancer progression and migration and targeting CB2R has been shown to reduce CXCR4-mediated mechanisms responsible for metastatic progression." (PMID 35204820, 2022). "Second, CXC-chemokine receptor 4 (CXCR4) signaling is potentially critical during VCO, as this pathway is involved in perivascular invasion of brain-metastasizing cancer cells through stimulation by brain EC-derived CXC-chemokine ligand 12 (CXCL12)." (PMID 36119528, 2022). "The levels of chemokine family members CXCR4 and CXCL-12, essential markers in the cancer microenvironment, were evaluated for protein and gene expressions." (PMID 36551144, 2022). "In the skeletal muscle of cancer patients, the expression of SDF1 and CXCR4 is inversely co-related to the expression of MURF1 and Atrogin-1." (PMID 36077789, 2022). "In summary, the activation of caspase-3/GSDME-dependent pyroptosis by nanostructured toxins targeting CXCR4 opens a novel and virtually unexplored therapeutic approach for HNSCC or other cancer types." (PMID 35120582, 2022). "Having found that the surfaces of cancer cells display CXCL12–KRT19 heterodimers that are polymerized by inclusion into filamentous networks, we wished to examine how ligation of CXCR4 by a multimeric form of CXCL12 would affect the motility of T cells." (PMID 35046049, 2022). "Changes in CXCL12 and CXCR4 levels in pre-nCRT biopsy and paired post-nCRT surgical specimen tissue samples from 45 LARC patients showed higher expression in LARC cancer cells after nCRT (p < 0.001 for each, Wilcoxon signed-rank test)." (PMID 34976180, 2022). "Our team discovered that cancer-originated DNA can activate the CXCL12-CXCR4 and CCL21-CCR7 axes in HCC cells, while sinoline treatment reduced the expressions of CXCL12, CXCR4, CCL21, and CCR7 in HCC cells." (PMID 35860597, 2022). "Angiogenesis plays a critical role in normal development and the progression of cancer and is closely related to the CXCL12/CXCR4 axis." (PMID 35893797, 2022). "Antagonizing these receptors and/or ligands provided novel platforms for cancer therapeutics: CCR7/CCL21 for lymph node metastases, and CXCR4/CXCL12 for lung, liver, bone marrow and brain metastases." (PMID 35203305, 2022). "We previously identified a subpopulation of NSCLC cancer stem cells (CSCs), characterized by the expression of CD133 and the chemokine receptor CXCR4, which was able to grow as spheres, and to initiate the metastatic process." (PMID 35563517, 2022). "Cancer stem cells (CSCs) play an important role in the maintenance, recurrence, metastasis, and drug resistance of CRC, and CD44, CD133, CD166, and CXCR4 are putative surface markers of colorectal CSCs." (PMID 35313878, 2022).